HIF1A (hypoxia inducible factor 1 subunit alpha)
Diseases named in the same sentence as HIF1A in open-access papers (continued):
Sharing a sentence is not in itself a finding about the gene and the disease.
tumor (continued). "It is suggested that HIF-1α and HIF-2α are likely to play different roles at different stages of tumour formation and progression and that these roles might potentially be modulated by the spectrum of mutations present in each individual ccRCC." (PMID 36364144, 2022). "Moreover, HMOX1/HO-1 (heme oxygenase 1) was reported to promote lung metastasis in mice, and its high expression was correlated with tumor invasiveness in NSCLC, as similarly reported for HIF-1α." (PMID 35688943, 2022). "In brief, HIF-1α promotes metabolic reprogramming in tumor cells and TME cells, while HIF-2α induces an aggressive stem-like phenotype within tumor cells, and both contribute to angiogenesis and the production of tumor-licensed TME." (PMID 36003773, 2022). "The hypoxic tumor microenvironment can favor the upregulation of CXCR4 and CXCL12 in several cell types such as endothelial cells and cancer cells through mobilization of the hypoxia induced factor 1 (HIF-1α)." (PMID 35406582, 2022). "HIF-1α and VEGF play a significant role in tumor angiogenesis." (PMID 36297535, 2022). "Moreover, the expression levels of hypoxia-inducible factor-1 alpha (HIF1A) and lactate dehydrogenase A (LDHA), were observably upregulated in tumor cells from solid LUADs." (PMID 36138435, 2022). "Endogenous HIF-1α promotes CD24 expression, as well as tumor formation and metastasis." (PMID 36014432, 2022). "However, the role of HIF1α in CRC tumor growth, tumor polyamine metabolism and intestinal mucosal barrier damage has not been studied." (PMID 35912204, 2022). "In addition, the intratumoral gene expression of HIF-1α, VEGF, P-glycoprotein, etc., could also be detected by enzyme-linked immunosorbent assay, western blot, or real-time quantitative polymerase chain reaction to further estimate the modulation of microenvironment after tumor reoxygenation." (PMID 35631488, 2022). "When HIF-1α was expressed, HIF-2α was suppressed and tumour growth was inhibited." (PMID 35572574, 2022). "Considering these data and existing knowledge on HIF1A, we hypothesized that SOCS5 promotes the expression of HIF1A and affects the hypoxic tumor microenvironment." (PMID 36319626, 2022). "MiR-497: The ectopic expression of hypoxia-responsive tumor suppressor miR-497 by targeting VEGF and HIF-1α could reduce tube formation and MVD in vitro and in vivo under hypoxia condition." (PMID 35499045, 2022). "In C57BL/6, but not NSG recipients, genetic depletion of Hif1a (sh-Hif1a) in E0771 cells significantly inhibited tumor growth compared with E0771 transduced with scrambled shRNA (sh-Scr) in mice of the same respective strains." (PMID 35239514, 2022). "HDAC4-AS1 regulates HIF-1α under hypoxic conditions to inhibit the transcriptional activity of HDAC4, thereby helping to reduce the toxicity of chemotherapeutics and inhibit tumor growth." (PMID 35371346, 2022). "For instance, PD-L1 and B7-H3 could enhance aerobic glycolysis in tumor cells by activating PI3K-AKT-mTOR pathway and HIF-1α." (PMID 36618408, 2022). "Thus the main function of HIF-1α is regulation of VEGF, secondly it contributes to the potentiation of tumour-induced immunosuppression." (PMID 35012617, 2022). "Both HIF-1α and VEGF play critical roles in angiogenesis and tumor progression." (PMID 35997665, 2022). "HIF1α stimulates vascular endothelial growth factor A (VEGFA) gene transcription, which promotes angiogenesis, thereby increasing nutrient availability and oxygen supply to hypoxic tumor areas." (PMID 35193955, 2022). "Primary tumours with IHC-staining positive for HIF-1α were similarly distributed in the RT and non-RT groups (27% and 31%, respectively)." (PMID 35140341, 2022).
tumor (continued). "Numerous studies have suggested that radiation breaks the DNA strands of tumor cells and increases the secretion of transforming growth factor-β (TGF-β) and hypoxia-inducible factor 1-α (HIF-1α), thus suppressing the immune system and inducing radio-resistance." (PMID 36338684, 2022). "HIF-1α and LOX promote tumor development in coordination with each other." (PMID 36419894, 2022). "The evidence suggests that HIF-1α-mediated autophagy in tumor cells supports cell survival but not cell death." (PMID 36551540, 2022). "The HIF-1a and HIF-2a expressions were different in relation to the tumor characteristics." (PMID 36294785, 2022). "In the ovarian cancer microenvironment, various factors can also regulate the expression of HIF-1α expression in nontumour cells and affect the malignant biological properties of tumour cells." (PMID 35004308, 2021). "However, it was demonstrated that Src attenuation by CBD caused the stabilization of VHL as well as the downregulation of HIF-1α and VEGF, followed by the inhibition of tumor angiogenesis under hypoxic conditions." (PMID 34830821, 2021). "Differentiation, recruitment, and polarization of TAMs may be regulated by tumor cells via VEGF-A, HIF-1α and CCL2-dependent mechanisms." (PMID 34025660, 2021). "ATR inhibition decreases HIF-1α expression and suppresses the expression of HIF-1-downstream genes, glucose transporter-1 (GLUT-1) and CAIX, under hypoxic conditions and exhibits antitumor effect in in vivo studies with OE21 tumor xenograft, among others." (PMID 34200019, 2021). "Depletion of HIF-1α decreases the cytotoxicity in NK cells, but significantly delays tumor growth via stimulating non-productive angiogenesis." (PMID 33514004, 2021). "MiR-195-5p is a multifunctional miRNA that acts as a tumour suppressor in CRC and has not only multiple targets that inhibit CRC cell migration by regulating EMT but also multiple targets that affect blood vessels, such as HIF-1α and VEGF." (PMID 33865381, 2021). "After tumor recurrence, iTreg, exhaustion, DC, monocyte, and infiltration scores were positively correlated with HIF1A expression, while the NKT and gamma-delta were negatively correlated with HIF1A expression." (PMID 34305618, 2021). "Notably, protein extracts were prepared from whole tumors, containing proteins expressed by tumor epithelial cells and the stroma, likely minimizing the total reduction in CKB because only the tumor epithelium lacks HIF-1α." (PMID 35008190, 2021). "Overexpression of HIF-1α induces the upregulation of angiogenic growth factors such as VEGF and promotes formation of tube by vascular endothelial cells and vasculogenic mimicry by tumor cells." (PMID 33505496, 2021). "However, our results indicate that in the peripheral blood, the expression of HIF-1α and GLUT1 cannot be considered as a tool for predictive evaluation or prediction of tumor aggressiveness." (PMID 33888756, 2021). "Therefore, a hypoxia-responsive lncRNA-SNHG12/miR-194-3p/TM4SF1 or HIF-1A ceRNA network is likely to present in the cancer tissues of HCC patients, and the ceRNA network is involved in tumor development and is related to patient prognosis." (PMID 33690171, 2021). "Immune cell numbers were not significantly different between tumor-bearing lungs of Hif1αf/f PyMT+ and Hif1α−/− PyMT+ mice either (red points)." (PMID 34556788, 2021). "As we observed upregulation of FOXC2 expression in hypoxic tumor cores, we first examined the expression of FOXC2 and HIF-1α in immortalized (HMLE) and RAS-transformed (HMLER) human mammary epithelial cells, following exposure to DFX, an iron chelator known to function as a hypoxia-mimetic." (PMID 33889304, 2021). "Exosomal miR-23 suppresses the expression of VHL to upregulate HIF-1α, GLUT-1, vascular endothelial growth factor (VEGF) and subsequently triggers the proliferation, metastasis, 5-FU resistance and other malignant biological behaviors of tumor cells." (PMID 33869059, 2021).
tumor (continued). "In CD8 T cells, the transcription factor HIF1α acts as a negative regulator of multiple chemokine receptors including CXCR3, which might suggest that tumour hypoxia could affect the tumour infiltration of cytotoxic lymphocytes." (PMID 34090499, 2021). "The declined expression of tumor growth-promoting IL-10, TGF-β, and VEGF could depend on the altered expression of their upstream regulators: HIF-1α and Hsp70." (PMID 33716751, 2021). "A combined on-tumor and off-tumor inhibition of HIF-1α was also observed in idelalisib-treated patients, who showed, along with a downregulation of HIF-1α target genes in leukemic cells, a significant decrease in CXCL12 serum concentration and changes in the bone marrow microenvironment." (PMID 34207596, 2021). "In terms of anti-tumor mechanism, CTP/CDDP could directly or indirectly inhibit the expression of HIF-1α, GSH and MRP2, reduce the efflux of CDDP and alleviate the chemotherapeutic drug resistance in tumor cells." (PMID 34399762, 2021). "Furthermore, HIF-1α-dependent upregulation of the NKp44 receptor in hypoxia-exposed NK cells resulted in increased killing against K562, CEM, and A375 tumor targets both in-vitro and in-vivo tumor clearance assays." (PMID 33920906, 2021). "A recent study has shown TECs isolated from hypoxic highly metastatic tumours contained more aneuploid cells, had enhanced proliferative and invasive capacity and had enhanced mRNA expression of pro-angiogenic (VEGF, VEGFR1/2, HIF-1α) and stemness genes than TECs derived from low metastatic tumours." (PMID 34099013, 2021). "Activation of HIF-1α can enhance glycolysis and decrease the tricarboxylic acid (TCA) cycle and OXPHOS, and it may stimulate tumor cell proliferation, apoptosis resistance, migration, and invasion in different tumor cell lines." (PMID 34220956, 2021). "We confirmed that HIF1α can negatively regulate the expression of GPD2 at the transcriptional level, thereby inhibiting tumor progression, which is new mechanism-of-action for HIF1α as a tumor suppressor." (PMID 34098990, 2021). "HIF-2α expression but not HIF-1α was related to poor outcome and tumor size, lymph node metastasis, tumor stage and histology." (PMID 33445709, 2021). "Later, the same research group found that tumour secreted WISP-1/CCN4 promotes angiogenesis in oral SCC by upregulating VEGF-A via the αvβ3/FAK/c-Src pathway, which transactivates the EGFR/ERK/HIF1-α signalling pathway in oral SCC cells and increases angiogenesis-related tumour growth in vivo." (PMID 34205668, 2021). "HIF-1α and GLUT1 gene expressions were detected in all the tested samples (blood and tumor)." (PMID 33888756, 2021). "Furthermore, HIFAL overexpression promotes tumor growth in vivo, while targeting both HIFAL and HIF-1α significantly reduces their effect on cancer growth." (PMID 33637716, 2021). "To establish the role of TXNIP and downstream genes HIF1α and IL1β in the biology of cRCC, we have applied immunohistochemistry to multi-tissue arrays containing tumours of 691 patients without detectable metastases at the time of operation." (PMID 34433833, 2021). "We also performed immunofluorescence staining of HIF-1α and cleaved caspase-3 to distinguish the extent of apoptotic death in the hypoxic and non-hypoxic regions of tumor xenografts." (PMID 33859738, 2021). "To determine the effects of curcumin on angiogenesis signaling molecules in AsT cells, we first investigated whether curcumin treatment changes the expression of HIF1α and VEGF, important pathways regulating tumor angiogenesis." (PMID 34758851, 2021). "Although HIF1α was shown to be the exclusive regulator of CAIX expression, little is known as to what upstream signaling network activates the HIF1α–CAIX axis to cope with tumor metabolic stress." (PMID 34685701, 2021).
tumor (continued). "As tumor lymphangiogenesis via maspin seems to be rather modulated by VEGF-C and its receptors VEGF-R2 and VEGF-R3 and by the Hipoxia-inducing factor (HIF-1α), while systemic metastases mainly occur via VEGF-A, the maspin-based tumor therapeutics should target these specific molecular endpoints." (PMID 33498377, 2021). "HIF-1α and HIF-2α function can overlap during tumor development." (PMID 34142021, 2021). "The suppressive effects of 2 and 7 on HIF‐1α‐mediated gene transcription were investigated based on changes in the mRNA levels of the HIF‐1α downstream targets VEGF, glucose transporter‐1 (Glut1), and erythropoietin (EPO), which are crucial for tumor progression and angiogenesis." (PMID 33955074, 2021). "Upregulation of HIF-1α within the tumor can lead to decreased expression of the natural killer group 2 member D (NKG2D) receptor on NK and T cells, leading to immune evasion and impaired tumor cell killing." (PMID 34503254, 2021). "LOX is another factor produced by MAFs to enhance metastatic tumor cells’ proliferative level, which can reprogram glucose metabolism of metastatic tumor cells via the protein kinase B (AKT)-p70S6K/ hypoxia inducible factor 1 subunit alpha (HIF1α) pathway." (PMID 34112258, 2021). "In the neoplastic niche, the non-leukemic cell component is also exposed to hypoxia and HIF-1α-dependent signalling, which contribute to the creation of an immunosuppressive and pro-tumor microenvironment." (PMID 34207596, 2021). "When hypoxic-irradiated tumor cells were pretreated with an HIF-1α inhibitor, the DNA damage in the non-irradiated bystander cells was attenuated, while cell survival of bystander cells was increased." (PMID 33869184, 2021). "The HIF-1α (Hypoxia Inducible Factor 1α)/VEGF/MMP signaling cascade activated by hypoxia and by ROS regulates the formation of new blood vessels promoting tumor formation." (PMID 34205998, 2021). "Therefore, overexpression of VCAN-AS1 promotes tumor growth and EMT by regulating the miR-106a-5p/STAT3/HIF-1α pathway." (PMID 34365889, 2021). "Previous studies have found that the AGE/RAGE signaling pathway activated the downstream HIF-1a and PI3K/AKT signaling pathways in the cell and then promoted tumor cell proliferation, migration, invasion, cloning, and spheroidization, which inhibited cell apoptosis and activated the EMT process." (PMID 34194533, 2021). "Additionally, the expression of SUCNR1, HIF-1α, succinate dehydrogenase (SDH) A, and SDHB was higher in the tumor tissue than in the matched normal mucosa." (PMID 33916314, 2021). "Thus, not only HIF1A, but also VEGFA, SLC2A1, and CA9 allow the tumor cells to survive in hypoxic environments and are well-established markers of cellular hypoxia." (PMID 33810575, 2021). "We then planned to study the mechanism by which HIF-1α regulates the migration and invasion of CAFs and whether inhibiting CAF metastasis could reduce tumor metastasis." (PMID 34631221, 2021). "Surprisingly, we found no discernible tumor burden present in the bone marrow of Hif1α−/− PyMT+ mice upon histological inspection by a certified veterinary pathologist, save in one mouse." (PMID 34556788, 2021). "It was concluded that curcumin administered in combination with Glu-GNPs and X-ray irradiation could reduce the protein expression of VEGF, HSP90, HIF-1α, and MMP9 in tumor tissue when compared with the model group." (PMID 34825004, 2021). "Such HIF-1α inhibition further suppresses hypoxia-mediated induction of monocyte chemoattractant protein-1 (MCP1), ultimately restricting the infiltration of TAMs into the tumor microenvironment and enhancing the effect of radiotherapy." (PMID 34575983, 2021).
tumor (continued). "After knocking out HIF1α and HIF2α at the same time, cell cycle arrest was inhibited, and the proportion of cells in the G2/M+S phase increased, thus contributing to GBM cell proliferation and the increase in tumour volume." (PMID 33986256, 2021). "Several studies have shown that HIF-1A is stabilized in the hypoxic tumor environment owing to the lack of molecular oxygen, which leads to the expression of HIF-1A target genes that in turn activate the expression of many genes involved in glucose metabolism." (PMID 33985530, 2021). "Finally, HIF1α and HIF2α regulate the malignant progression of GBM through the EGFR–PI3K/AKT pathway with positive feedback, which provides a new tumour development model and a new strategy for treating GBM." (PMID 33762574, 2021). "There is some evidence for the stronger induction of CSCs by HIF-1α in hypoxic areas during tumor development, and for HIF-2α as the main HIF factor under normoxic conditions that follow after cancer therapy, leading to a reduction in tumor size." (PMID 33472628, 2021). "Moreover, HIF‐1α‐expressed CAFs secreted CCL5 by activating NF‐κB signalling pathway, thus promoting the tumour growth of LC." (PMID 33943003, 2021). "In OSCC, HIF-1α and HIF-2α correlate positively with clinical–pathological parameters, such as tumor size and micro vessel density, and in vivo experiments have shown their knockdown to reduce tumor angiogenesis and tumor growth." (PMID 35047997, 2021). "In sum, our work uncovers a complex role for IL-6 in regulation of tumor immunity: IL-6 induces alternative Mφ polarization and anti-inflammatory immune suppression, whereas it stimulates pro-inflammatory CD40 expression via Stat3/HIF-1α in GBM." (PMID 34103524, 2021). "In addition, CTP/CDDP enhanced the expression of RKIP and inhibited the HIF-1α/MMP9 pathway by releasing NO and COS in hypoxic cells, thus inhibiting the EMT process of tumor and enhancing the anti-metastatic effect of chemotherapeutic drugs." (PMID 34399762, 2021). "Many studies have revealed that hypoxia-inducible factor-1α (HIF-1α) is the main component that makes various decisions to attain a more hostile environment for proper growth and development of tumor cells even in the absence of oxygen." (PMID 34869321, 2021). "This is further demonstrated in RCC tumor tissue where BNIP3 and VHL expression levels are lower compared to adjacent non-tumor tissues, whereas the expression of HIF-1α was higher in the same tumor tissues." (PMID 33573362, 2021). "STAT3 is a well-characterized oncogene that affects various biological processes, including promoting cell proliferation and survival by regulating Cyclin D1 and Bcl-2, inducing tumor invasion and metastasis by regulating E-cadherin and MMP-9, and promoting angiogenesis by HIF-1α expression." (PMID 34365889, 2021). "Unexpectedly, Hif1α deletion increases metastatic tumor burden in the lung, while deletion of Hif2α or Vhl does not affect pulmonary metastasis." (PMID 34556788, 2021). "Activated HIF-1α can up-regulate multiple cytokines such as vascular endothelial growth factor (VEGF), which in turn stimulates the development of new blood vessels to enrich tumor cell growth with oxygen." (PMID 33819917, 2021). "A non-significant trend in increased tumor burden was observed in the contralateral lung of Hif1α−/− PyMT+ mice by Pymt transcript levels." (PMID 34556788, 2021). "Unlike the Hif1α−/− PyMT+ mice, lung metastatic tumor burden in Hif2α−/− PyMT+ mice was not significantly different than Hif2αf/f PyMT+ mice, as measured by lesion number, total lesion area, individual lesion area, or incidence of lung metastases." (PMID 34556788, 2021). "In this sense, VHL-mediated HIF-1α and HIF-2α stabilization blunts the differentiation of CD8 T cells in vitro but increases GZMB expression, promoting the capacity of these cells to control tumor growth and persistent viral infections." (PMID 34025660, 2021).